STIM1 (stromal interaction molecule 1)
Diseases named in the same sentence as STIM1 in open-access papers (continued):
Sharing a sentence is not in itself a finding about the gene and the disease.
Immunodeficiency (continued). "Mutations in STIM1 and ORAI1, the genes that encode the functional channel, are tightly linked to a CRAC channelopathy in humans, which encompasses severe combined immune deficiency, myopathy and anhidrotic ectodermal dysplasia." (PMID 40459545, 2025). "Any disturbance of STIM1 activation leads to serious human diseases such as immunodeficiency or autoimmunity." (PMID 36691702, 2023). "As a major Ca2+ signaling regulator, STIM1 is involved in a number of pathologies, including neurodegenerative diseases, severe immunodeficiency, and cancer." (PMID 32916960, 2020). "It has been shown that STIM1 is required for SOCE in immune cells and loss of function or null mutations in human STIM1 gene stops Ca2+ influx in T cells resulting in immunodeficiencies in affected patients." (PMID 26732345, 2015). "The importance of SOCE in normal immune physiology has already been demonstrated in families with mutations in STIM1, STIM2 and Orai1 who demonstrate a severe immunodeficiency that causes bacterial, viral and fungal infections." (PMID 24000152, 2013). "This is evidenced by phenotype observations in patients or animal models with abnormal ORAI1 or STIM1 expression, which shows compromised CD4+ and CD8+ T cell functions related with humoral and cellular immunity, ultimately leading to immunodeficiencies and susceptibility to severe infections." (PMID 38791278, 2024). "Furthermore, several STIM1 loss-of-function mutations have been identified which lead to moderate or complete impairment of CRAC activation and are associated with immune deficiency, impaired enamel formation, or nail dysplasia, among other disorders." (PMID 37759684, 2023). "Clinical presentation does, however, vary greatly in STIM1 deficiency, with several STIM1-deficient patients described with late-onset or absent clinical immunodeficiency." (PMID 36302985, 2023). "Thus, Orai1 and other components of SOCE, e.g. stromal interaction molecules 1 and 2 (STIM1 and 2) represent interesting therapeutic targets for T cell-mediated (auto)immune diseases." (PMID 37150482, 2023). "Recessive STIM1 and ORAI1 loss-of-function (LoF) mutations inhibit SOCE and Ca2+ store refill and cause immunodeficiency (IMD9 and IMD10, OMIM # 612782, #612783), characterized by recurrent and chronic infections, autoimmunity, muscular hypotonia, mydriasis, and amelogenesis imperfecta." (PMID 35805973, 2022). "Other disease-related loss-of-function mutants include for instance STIM1 R426L, associated with enamel maturation or STIM1 E136X, which truncates STIM1 at the beginning of the SAM domain, and has been associated with severe immunodeficiency." (PMID 33333945, 2020). "In humans, autosomal-recessive mutations in the STIM1 result in combined immunodeficiency, immunodysregulation, ectodermal dysplasia, and nonprogressive myopathy." (PMID 29145451, 2017). "In fact, patients with STIM1 deficiency suffered from nonprogressive myopathy and immunodeficiency, and those with constitutive activation of STIM1 exhibited tubular-aggregate myopathy." (PMID 29145451, 2017). "The patient’s immunodeficiency and his other non–immune-related symptoms including thermoregulatory instability (indicative of anhidrosis) and muscular hypotonia are consistent with CRAC channelopathy disease reported in other patients with LOF mutations in ORAI1 and STIM1 genes." (PMID 41200103, 2025). "In this way, STIM1 is a key regulator of Ca2+ signaling in excitable and non-excitable cells, and altered STIM1 levels have been reported to underlie several pathologies, including immunodeficiency, neurodegenerative diseases, and cancer." (PMID 32916960, 2020). "Alterations in STIM1/Orai1 system may contribute to several pathophysiological conditions including cardiovascular and pulmonary diseases, hypertension, immunodeficiency, and autoimmune and lymphoproliferative diseases." (PMID 26064953, 2015).
Immunodeficiency (continued). "MHC Class II defect and defects in STIM1, DOCK2, SP110, ZAP70, and STK4 genes are categorized as combined immunodeficiencies as per the 2019 International Union of Immunological Societies Expert Committee classification of human inborn errors of immunity (IEI)." (PMID 33628209, 2020). "STIM1 mutations with a loss of STIM1 function result in the absence of SOCE and severe immune deficiency in human." (PMID 30262862, 2018).
tubular aggregate myopathy (28 papers, 2016 to 2026). "Tubular Aggregates Myopathy (TAM) due to STIM1 (stromal interaction molecule 1) gene mutations is a congenital myopathy, clinically characterized by skeletal muscle weakness, myalgias and cramps." (PMID 37155641, 2023). "We investigated STIM1 residues that are associated with tubular aggregate myopathy when mutated (F108I, H109N/R, I115F)." (PMID 32575830, 2020). "Here, we link tubular aggregate myopathy (TAM) mutations in STIM1 to their role in destabilizing the hydrophobic pocket and in promoting autophagic pathways." (PMID 32575830, 2020). "Gain‐of‐function mutations in STIM1 or ORAI1 isoforms cause tubular aggregate myopathy (TAM), a skeletal muscle disorder with muscular pain, weakness and cramping." (PMID 30382595, 2019). "Patients with one of four STIM1 missense mutations in EF-hand (constitutively active STIM1 mutants, H72Q, D84G, H109N or H109R) show muscular atrophy, tubular aggregate myopathy, and/or progressive muscle weakness." (PMID 29263348, 2017). "Mutations in Orai1 and STIM1 have been identified in patients with tubular aggregate myopathy (TAM), a rare genetic disease characterized by accumulation, in type-2 fibers, of highly ordered membrane tubules containing SR proteins, such as CASQ1, SERCA, triadin, RyR1, and STIM1." (PMID 35454077, 2022). "Gain-of -function mutations in STIM1 and Orai1 are increasingly recognized as a genetic syndrome that includes hyposplenism, platelet bleeding diathesis, and tubular aggregate myopathy (TAM1)." (PMID 38300705, 2024). "Any modifications in the SOCE process resulting in disease and mutations in STIM1 and ORAI1 have been linked to tubular aggregate myopathy in humans." (PMID 40841884, 2025). "Tubular aggregate myopathy (TAM) is caused by mutations in ORAI1 and STIM1 subunits of the Ca2+-release-activated Ca2+ (CRAC) channel." (PMID 39420094, 2024). "Recently, mutations in genes encoding two major proteins in SOCE, stromal interaction molecule 1 (STIM1) and calcium release-activated calcium channel protein 1 (ORAI1), have been identified as a cause of tubular aggregate myopathy (TAM)." (PMID 27879676, 2016). "On the other hand, dominant gain-of-function (GoF) mutations in the STIM1 and ORAI1 proteins lead to enhanced SOCE function and constitutive Ca2+ entry in the absence of ER/SR store depletion that results in tubular aggregate myopathy (TAM)." (PMID 39420094, 2024). "In contrast, alterations in the DES - STIM1 complex might contribute to the pathogenesis of tubular aggregate myopathy (TAM)." (PMID 37732119, 2023). "The pathogenic Orai1 L138F mutation located in TM2 was identified using whole exome sequencing in a Japanese family with tubular aggregate myopathy (TAM) and was found to mediate STIM1-independent Ca2+ entry." (PMID 36806330, 2023).
prostate carcinoma (27 papers, 2007 to 2024). A carcinoma that arises from epithelial cells of the prostate gland. "The clinical diagnostic and prognostic potential of Orai1 and STIM1 have also been demonstrated in many cancer types, including prostate cancer, melanoma, NSCLC, and colorectal cancer." (PMID 27677589, 2016). "We found that the vast majority of prostate cancer CTCs had simultaneously both STIM1 and ORAI1 overexpression (94%)." (PMID 38903530, 2024). "This is also in line with a previous study showing that STIM1 mediates cell invasion and bone metastasis in prostate cancer patients." (PMID 38903530, 2024). "According to previous publications from our group and other research teams, STIM1 and ORAI1 are implicated in metastasis of prostate cancer, as it has been shown to promote invasion, migration, and EMT in prostate cancer cells." (PMID 38903530, 2024). "For instance, H2O2 reduces SOCE current in prostate cancer cell lines and human platelets, and increases mRNA expression of Orai1 and Stim1 in bovine brain capillary endothelial cells." (PMID 39606036, 2024). "Knockdown of STIM1 in prostate cancer cells was related to EMT suppression and in breast and lung cancer cells the expression of E-cadherin, Snail and Vimentin were regulated by STIM1/2 expression." (PMID 34069353, 2021). "Several previous studies explored the possible role of SOCE/STIM1/Orai1 in autophagy using certain cell types including hepatoma cells, prostate cancer cells, and endothelial progenitor cells; however, the conclusions were inconsistent." (PMID 34079454, 2021). "CRACR2A in co-regulation with STIM1 and Orai1 has been recently suggested to potentially act as an upstream regulator of prostate cancer progression." (PMID 33333945, 2020). "Similar SOCE elevations were also seen in STIM1 + Orai1-OE and only STIM1-OE DU145 (prostate cancer cell line) and HEK (human embryonic kidney) cells, respectively." (PMID 31366337, 2019). "Resveratrol has been reported to promote autophagy in prostate cancer cells by down-regulating STIM1 and down-regulating SOCE, but the expression of ORAI1 and TRPC1 was not affected during this process." (PMID 31426853, 2019). "It has been possible to establish the involvement of TRPV6 in SOCE in prostate cancer cells, as well as its physical association with ORAI1 via STIM1 and TRPC1 under the conditions of SOCE." (PMID 29671777, 2018). "STIM1 and Orai1 expression levels are differentially regulated depending on the prostate cancer stage." (PMID 29951353, 2017). "Resveratrol‐activated autophagy mediated cell death in prostate cancer cells via downregulating of STIM1 and mTOR pathway." (PMID 28675698, 2017). "In early clinically localized cancer stages, STIM1 and Orai1 expression is increased, while in the later castration-resistant prostate cancer stages, their expression levels are decreased." (PMID 29951353, 2017). "We also noticed that the averaged Gleason score reduced when STIM1 was expressed at higher levels in prostate cancer tissues, suggesting the inhibitory role of STIM1 to development of advanced tumor." (PMID 26257076, 2015). "SOCE activity was also lower in PC3 than in LNCaP and DU145 cells, indicating that STIM1 has dynamic functions during prostate cancer progression." (PMID 26257076, 2015). "Previously, knock-down of STIM1 has been shown to suppress the expression of proteins important for epithelial-mesenchymal transition and enhance the expression of E-cadherin in human prostate cancer cells." (PMID 34155535, 2021). "In addition, resveratrol stimulates ACD in prostate cancer cells via down-regulation of STIM1 and the mTOR pathway." (PMID 33805467, 2021). "Similarly, in prostate cancer cells Orai1 knockdown inhibited apoptosis and STIM1 or Orai1 expression enhances cell senescence, thus supporting a role for SOCE in cancer cell death." (PMID 34069353, 2021).
prostate carcinoma (continued). "Moreover, the expression levels of STIM1 and Orai1 and other homologs are found to be differentially regulated based on the prostate cancer stage." (PMID 33333945, 2020). "Genetic silencing of STIM1/Orai1 and STIM1/Orai3 protein complexes by siRNA interference has, for example, yielded promising reductions in tumour progression and metastasis in xenograft models of breast, cervical and prostate cancer." (PMID 33036292, 2020). "Thus, our study revealed novel regulatory effects and the mechanisms by which STIM1 affects cell senescence, tumor migration and the tumor microenvironment, revealing that STIM1 has multiple functions in prostate cancer cells." (PMID 26257076, 2015). "We found that STIM1 expression is higher in the three prostate cancer cell lines than in BPH-1, suggesting that STIM1 may play a significant role in the development of human prostate cancer." (PMID 26257076, 2015). "To test this hypothesis, we studied the possible effect of STIM1 on regulating the secretion of cytokines in prostate cancer cells using the cytokine array." (PMID 26257076, 2015). "Based on the previous data the current study investigated at protein level the expression of ORAI1, STIM1, and KDM2B in CTCs from prostate cancer patients." (PMID 38903530, 2024). "We have also recently shown that overexpression of KDM2B in prostate cancer cells resulted in a significant upregulation of ORAI1 and Stim1 transcription." (PMID 38903530, 2024). "The expression of STIM1 and ORAI1 in prostate cancer CTCs was examined by immunofluorescence using antibodies for CK, STIM1, and ORAI1." (PMID 38903530, 2024). "STIM1 overexpression has been shown to promote cell migration and EMT through TGF-β, Snail and Wnt/β-Catenin signaling in prostate cancer cell lines of PC-3 and DU-145." (PMID 38903530, 2024). "Both STIM1 and ORAI1 were found to be overexpressed in both prostate cancer cell lines, while in PBMCs the expression of STIM1 and ORAI1 was very low or absent, implying that both biomarkers are specific for tumor cells in the bloodstream." (PMID 38903530, 2024). "STIM1 and SOX2 were discovered to have anti-apoptotic effects in pancreatic cancer cell lines, HCC, and prostate cancer." (PMID 38532463, 2024). "In contrast, in prostate cancer cell lines (LNCaP, PC3 and DU145) STIM1 was expressed at higher levels compared with the hyperplasia cell line BPH-1 and this was associated with higher SOCE levels." (PMID 34069353, 2021). "On the other hand, in prostate cancer cells (DU145 and PC3), resveratrol has been proposed to induce autophagy by regulating the function of STIM1 and then SOCE." (PMID 33424550, 2020). "In androgen-independent prostate cancer cells, resveratrol induces autophagy-mediated cell death through regulation of store-operated Ca2+ entry (SOCE) mechanisms, and down-regulation of stromal interaction molecule 1 (STIM1) expression." (PMID 32070025, 2020). "A recent study reported that resveratrol induced autophagic cell death of human prostate cancer cells through regulating SOCE pathways, including downregulating STIM1 expression and decreasing ER Ca2+ stores." (PMID 31252656, 2019). "The essential role of the functional coupling of STIM1 to Orai1, as well as STIM1/Orai1-dependent SOCE, in promoting apoptosis was firstly demonstrated in the study on prostate cancer cells." (PMID 31252656, 2019). "It was found that the expression of both STIM1 and ORAI1 correlated negatively with the Gleason score (the commonly used histopathological assessment of prostate cancer progression) and was lower in prostate carcinomas relative to the normal tissue." (PMID 29671777, 2018). "The recent characterization of store-operated calcium entry (SOCE) channel components STIM1 and ORAI1 in prostate cancer sheds light on the involvement of calcium in these processes." (PMID 29671777, 2018).
prostate carcinoma (continued). "This article summarizes what is known about the dysregulation of the key molecular players involved in SOCE (STIM1, STIM2, Orai1, Orai2, and Orai3) and the negative regulator TRPM4 in prostate cancer." (PMID 29951353, 2017). "In prostate cancer cells, activation of SOCE reduces autophagosome formation, whereas inhibition of Stim1 expression and SOCE results in autophagic cell death." (PMID 27878958, 2017). "We here summarize findings on gene expression levels and functions of SOCE components, stromal interaction molecules (STIM1 and STIM2), and members of the Orai protein family (Orai1, 2, and 3) in prostate cancer." (PMID 29951353, 2017). "In this study, we explored the role of STIM1 and ORAI1 in tumor senescence, migration and microenvironment and demonstrated their dual functions during prostate cancer progression." (PMID 26257076, 2015). "To further investigate the role of STIM1 and ORAI1 in prostate cancer, we established DU145 and PC3 cell lines that stably overexpressed STIM1-YFP and/or ORAI1." (PMID 26257076, 2015). "STIM1 knockdown inhibited migration and invasion of PC-3 and DU-145 cells through the inactivation of PI3K/Akt signaling pathway while it was also proposed as a potential target against prostate cancer metastasis." (PMID 38903530, 2024). "While ARC activation is dependent on STIM1 in HEK293 cells, in prostate cancer cells, silencing of the STIM1 expression did not alter the ARC activation, suggesting a STIM1-independent mechanism." (PMID 35682546, 2022). "All these data suggest that the overexpression of STIM1 and/or ORAI1 may promote cell senescence in prostate cancer cells." (PMID 26257076, 2015). "In addition, STIM1 overexpression significantly promoted the epithelial-to-mesenchymal transition (EMT) and increased the migration of human prostate cancer cell lines in remodeled tumor microenvironments." (PMID 26257076, 2015). "We thus determined relative STIM and Orai expression levels in non-tumorous and tumorous tissue from 13 prostate cancer patients by qRT-PCR, from which 13 expressed detectable levels of STIM1, STIM2 and Orai1 and 11 detectable levels of Orai2 and Orai3." (PMID 24240085, 2013). "We compare expression levels of STIM1, STIM2, Orai1, Orai2 and Orai3 in tumorous and non-tumorous tissue from prostate cancer patients." (PMID 24240085, 2013).